BDNF (brain derived neurotrophic factor)
Diseases named in the same sentence as BDNF in open-access papers (continued):
Sharing a sentence is not in itself a finding about the gene and the disease.
anxiety disorder (116 papers, 2013 to 2025). A category of psychiatric disorders which are characterized by anxious feelings or fear often accompanied by physical symptoms associated with anxiety. "Brain-derived neurotrophic factor, a neurotrophic factor produced by skeletal muscle, is associated with anxiety disorders." (PMID 40951397, 2025). "Decreased BDNF signaling in brain regions like the prefrontal cortex, amygdala, and hippocampus has been associated with the development of anxiety disorders." (PMID 38988101, 2024). "Several studies have explored the potential role of BDNF in anxiety disorders, aiming to elucidate its association with the pathophysiology of this condition." (PMID 38376041, 2024). "According to the Ingenuity Pathway Analysis (IPA) database (licence ID: 46874), the Venn diagram indicated that MSC-secreted protein, brain-derived neurotrophic factor (BDNF), was associated with major depressive and anxiety disorders." (PMID 37973914, 2023). "Recently, Val66Met, a single nucleotide polymorphism of the coding region of the BDNF gene has been identified as a risk factor for anxiety disorders and post-traumatic stress disorder." (PMID 36614034, 2022). "The common brain-derived neurotrophic factor (BDNF) Val66Met polymorphism is associated with reduced activity-dependent BDNF release and increased risk for anxiety disorders and PTSD." (PMID 35256586, 2022). "Further, the neurotrophic factor Brain Derived Neurotrophic Factor (BDNF) is implicated in mood and anxiety disorders and is upregulated by antidepressants." (PMID 34368117, 2021). "Overlap exists in some common genetic variants (BDNF gene, for example) found across the affective/anxiety disorder spectrums." (PMID 35095581, 2021). "Brain-derived neurotrophic factor (BDNF) plays an important role in neuronal plasticity, and its dysregulation has been associated with the pathogenesis of mood and anxiety disorders." (PMID 32116853, 2020). "Numerous genetic, pharmacological and behavioral studies have linked the dysregulation of BDNF to major psychiatric and neurological disorders, including mood and anxiety disorders." (PMID 32116853, 2020). "BDNF is one of the most inspiring molecules to better understand the disadvantageous synaptic learning underlying the etiology of anxiety disorders and the beneficial synaptic mechanisms underlying extinction learning." (PMID 28280960, 2017). "Impaired regulation of BDNF expression has been implicated in mood and anxiety disorders and in cognitive and neurodegenerative diseases; environment stimuli such as H2O2 reduced BDNF expression levels in SH-SY5Y cells." (PMID 26649298, 2015). "Dysregulation of brain-derived neurotrophic factor (BDNF), behavioral inhibition temperament (BI), and small hippocampal volume have been linked to anxiety disorders." (PMID 26257661, 2015). "Recently, a single nucleotide polymorphism (SNP) of the coding region of the BDNF gene (Val66Met) has been identified as a risk factor for anxiety disorders, including post-traumatic stress disorder (PTSD)." (PMID 26257661, 2015). "Our arguments are in agreement with a meta-analysis that concluded that BDNF Met/Met homozygous Asians are predisposed to a sub-significantly higher risk of anxiety disorders." (PMID 25383981, 2014). "In addition to analyzing the correlation between gut flora structure and anxiety disorders, the study also included an analysis of inflammation and polymorphisms of the brain-derived neurotrophic factor (BDNF) gene." (PMID 40289955, 2025). "BDNF and its receptor, Tropomyosin-Related Kinase B (TrkB), are found within brain structures involved in learning and memory, such as the cortex, hypothalamus, hippocampus, and amygdala, each of which has also been implicated in anxiety disorders and PTSD." (PMID 37491857, 2024).
anxiety disorder (continued). "Experimental evidence suggests that anxiety disorders are associated with decreased serotonergic, upregulated dopaminergic transmission, and low levels of the brain-derived neurotrophic factor (BDNF)." (PMID 38543047, 2024). "Thus, the knockdown of the regulator of calcineurin 1 (RCAN1)—a protein regulating the calcium/calmodulin-dependent phosphatase calcineurin implicated in human anxiety disorders—increased in mice pCREB and BDNF levels." (PMID 25505876, 2014). "Moreover, BDNF level changes in serum are associated with anxiety disorders." (PMID 37181876, 2023). "Furthermore, in humans, BDNF and TrkB signaling has been associated with a multitude of psychiatric diseases and is therefore widely studied in the context of schizophrenia, autism, depression, addiction, or anxiety disorders." (PMID 28280960, 2017). "Considering that skeletal muscle contractions release neurotrophic factors, such as BDNF, it can be assumed that these contractions are related to anxiety disorders." (PMID 40373026, 2025). "Among the various psychiatric and neurological illnesses that BDNF affects is the pathophysiology of anxiety disorders, where it plays a significant role." (PMID 39195700, 2024). "In line with our findings, their results demonstrated a significant decrease in BDNF levels among individuals with anxiety disorders." (PMID 38376041, 2024). "Currently, the function of BDNF-TrkB pathway in anxiety disorders has received increasing attention." (PMID 35543383, 2022). "It has been reported that BDNF-TrkB signaling pathway is closely related to the occurrence and development of anxiety disorders through interaction with other pathways." (PMID 35543383, 2022). "Experimental studies suggest a link between impaired hippocampal BDNF systems and anxiety disorders." (PMID 36159923, 2022). "Platelet 5-hydroxytryptamine (5-HT, serotonin)-reuptake-site binding was decreased and brain-derived neurotrophic factor (BDNF) downregulated in patients with anxiety disorders." (PMID 34276303, 2021). "BDNF is closely related to the pathophysiology of anxiety disorders and has been used as a potential target for many antianxiety drugs." (PMID 32655658, 2020). "BDNF is one of the most widely studied neurotrophic factors in anxiety disorders and is related with neuroplasticity cellular mechanism." (PMID 32655658, 2020). "In clinical and animal models, BDNF has been associated with the development of affective disorders including MDD, anxiety disorders, and posttraumatic stress disorders." (PMID 32655658, 2020). "In humans, downregulation of BDNF has been related to mood and anxiety disorders, while high BDNF concentration has appeared to be a resiliency factor." (PMID 33408651, 2020). "In summary, an impaired BDNF system is a vulnerability factor for anxiety disorders and affects normal hippocampal function." (PMID 26257661, 2015). "In contrast, few studies were conducted to explore serum BDNF as a biomarker in patients with anxiety disorders." (PMID 26539329, 2015). "The authors found evidence for reduced peripheral BDNF levels in patients with anxiety disorders, mostly due to effects in those suffering from OCD." (PMID 25932008, 2015). "On the other hand, we found an elevated prevalence of comorbid psychiatric disorders in these patients with polysubstance use and changes in BDNF concentrations related to the diagnosis of mood and anxiety disorders." (PMID 25734326, 2015). "The hippocampus was the focus of this study because it contains a high amount of BDNF, and dysfunction of hippocampus and BDNF systems both represent vulnerabilities for developing anxiety disorders." (PMID 26257661, 2015). "Foot-shock stress leads to reductions of BDNF levels, arguing for a link between BDNF and anxiety disorders such as post-traumatic stress disorder." (PMID 25932008, 2015).
anxiety disorder (continued). "We have indeed observed in this study changes in circulating concentrations of these neurotrophic factors in mood and anxiety disorders, especially in BDNF." (PMID 25734326, 2015). "It has been demonstrated that BDNF is involved both in the pathogenesis and treatment of anxiety disorders." (PMID 24690945, 2014). "Psychiatric disorders are expected to affect the association of the PPT and serum mediators studied; however, only the obsessive compulsive disorder, which is a component of the spectrum of anxiety disorders, showed an effect on serum BDNF." (PMID 25005881, 2014). "Effect sizes of the differences in BDNF levels between anxiety disorder and control groups were calculated." (PMID 23908608, 2013). "Studies that measured BDNF protein levels in any anxiety disorder and compared these to a control group were included." (PMID 23908608, 2013). "One interventional study assessed BDNF levels in patients with Panic Disorder and one in a combined group of anxiety disorder patients." (PMID 23908608, 2013). "When results of all studies were combined, there was a significant difference between groups with lower BDNF levels in patients with an anxiety disorder [SMD = −0.94 (−1.75, −0.12); z = 2.25, p = 0.02]." (PMID 23908608, 2013). "As findings of BDNF levels in anxiety disorders have been inconsistent, we undertook to conduct a systematic review and meta-analysis of studies that assessed BDNF protein levels in these disorders." (PMID 23908608, 2013). "Sensitivity analyses of serum studies yielded a different result, although there was a trend toward significance for lower BDNF levels in the anxiety disorders [SMD = −1.06 (−2.27, 0.16); z = 1.70, p = 0.09]." (PMID 23908608, 2013). "Findings of BDNF protein levels in anxiety disorders, in animal models and in humans have, however, been inconsistent." (PMID 23908608, 2013). "While a variety of animal models of fear and anxiety disorders have demonstrated epigenetic regulation of BDNF, only a few studies have revealed the potential role for epigenetic regulation of BDNF in human clinical populations." (PMID 23847551, 2013). "Clarifying these findings is important in elucidating the relevance and clinical application of BDNF measures in the diagnosis and treatment of anxiety disorders." (PMID 23908608, 2013). "We conducted a comprehensive search to identify studies related to our research question and believe that our review gives the most comprehensive overview of BDNF in anxiety disorders to date." (PMID 23908608, 2013). "Although BDNF levels tend to be reduced in anxiety disorders, this trend is inconsistent." (PMID 40491453, 2025). "Conceivably reduced BDNF release in Met carriers could disrupt fear extinction or lead to fear or anxiety disorders." (PMID 40362507, 2025). "Additionally, the direct relationship of BDNF to neuroplasticity, cognitive function, and stress/anxiety disorders was considered." (PMID 41286328, 2025). "Since BDNF plays a role in the fear extinction enhancement, targeting the impaired extinction in anxiety disorders such as PTSD via BDNF signaling may be an important and novel way to enhance treatment efficacy." (PMID 36647145, 2023). "Third, although state anxiety, serum BDNF levels, and panic severity could predict changes in somatic symptoms in PD, these predictive factors only explained 31.3% of the regression model." (PMID 37533888, 2023). "Therefore, the change in BDNF expression level is closely related to the occurrence of anxiety disorder." (PMID 37118929, 2023). "State anxiety, serum BDNF levels, and panic severity could predict changes in somatic symptoms post-escitalopram treatment, our results highlighted that serum BDNF could serve as a biological indicator for improving somatic symptoms in PD patients." (PMID 37533888, 2023). "Patients with anxiety disorder have lower central and peripheral levels of BDNF." (PMID 35563336, 2022).
anxiety disorder (continued). "The BDNF gene has been studied in relation to anxiety disorders such as PTSD." (PMID 34239411, 2021). "Fluoxetine is a widely used antidepressant in treatment of mood and anxiety disorders via regulating miR-29 family and genes such as brain derived neurotrophic factor (BDNF), response regulator in two-component regulatory system with CreC (CREB), and HUS-associated diffuse adherence (HDACs)." (PMID 29495532, 2018). "Previous studies have shown a reduced expression of BDNF in relation to anxiety disorders and OCD, which could be caused by a possible differential methylation in the BDNF gene." (PMID 27047397, 2016). "In addition, the possible effect of the SNP rs6265 (Val66Met) was investigated in relation to BDNF levels and presence of anxiety disorders." (PMID 26539329, 2015). "Thus, plasma BDNF concentrations were reduced in cocaine users diagnosed with both primary and cocaine-induced mood and anxiety disorders." (PMID 25734326, 2015). "Additionally, the decrease in BDNF concentrations in subjects diagnosed with both primary and cocaine-induced anxiety disorders were also significant (p<0.05) relative to the control group." (PMID 25734326, 2015). "Interestingly, plasma BDNF concentrations were exclusively found to be decreased in users diagnosed with both primary and cocaine-induced disorders for mood and anxiety disorders." (PMID 25734326, 2015). "Thus, there has been much interest in verifying if, across multiple psychiatric disorders, including anxiety disorders, BDNF can be used as a biomarker." (PMID 25932008, 2015). "Interestingly, previous studies have demonstrated that in addition to NPY-ergic system, BDNF also interacts with the HPA axis, and therefore, it has been implicated in the etiology of anxiety disorders and PTSD." (PMID 26016844, 2015). "Results of this review and meta-analyses, focusing on BDNF protein levels from serum, plasma and CSF, indicate that lowered levels of BDNF in participants with anxiety disorders in comparison to controls is due to significantly lowered levels of BDNF in patients with OCD." (PMID 23908608, 2013). "Therefore, correlation between BDNF and alteration of ReHo may be a characteristic manifestation of HIV-associated anxiety disorders." (PMID 38563030, 2024). "Importantly, BDNF exerts beneficial effects in the setting of depressive and anxiety disorders." (PMID 37415688, 2023). "Studies have reported the association of abnormal levels of serotonin, dopamine and norepinephrine, as well as the lower levels of BDNF, to various depressive and anxiety disorders, which might serve as another plausible reason for the pathophysiology observed therein." (PMID 35236424, 2022). "In the infralimbic medial prefrontal cortex, STDP is absent in a rodent model (BDNF-Met/Met mice) of the human BDNF Val66Met polymorphism (leading to severe cognitive dysfunction and anxiety disorders) in which the BDNF release is impacted; STDP is recovered after exogenous BDNF application." (PMID 30018546, 2018). "However, inhibited temperament may interact with either BDNF/hippocampal dysfunction to exacerbate vulnerability to develop anxiety disorders." (PMID 26257661, 2015). "We also anticipate that levels of hormones such as asprosin and BDNF may serve as early indicators and biomarkers for addressing risk factors associated with clinical conditions closely associated with BGN, such as eating disorders, anxiety disorders, and body dysmorphic disorders." (PMID 41286328, 2025). "Practicing yoga can reduce symptoms of anxiety disorders by regulating the HPA (hypothalamic–pituitary–adrenal) axis and increasing the level of brain-derived neurotrophic factor (BDNF), which supports neuroplasticity." (PMID 39329885, 2024). "An analysis of 36 biomarkers (including leptin, brain-derived neurotrophic factor [BDNF], and tryptophan) demonstrated higher rates of anxiety disorders in individuals with metabolic disturbances." (PMID 37840785, 2023).
anxiety disorder (continued). "Higher baseline serum BDNF and 5-HIAA or those with a history of anxiety disorder showed a higher reduction in pain scores across time." (PMID 36013137, 2022). "Antianxiety behavior associated with the brain-derived neurotrophic factor-mammalian target of rapamycin signaling pathway was revealed by knockdown of HCN1 channels in the hippocampal dorsal CA1 region, suggesting that HCN1 protein might be a target for anxiety disorder treatment." (PMID 35372451, 2022). "We found that plasma BDNF, IGF-1 and IGFBP-3 are unaltered in abstinent cocaine users but they are affected by the presence of comorbid mood and anxiety disorders." (PMID 25734326, 2015). "We sought, firstly, to assess whether BDNF protein levels were lower in individuals with anxiety disorders than in those without, and secondly whether there was any specificity of effect with regards to the different anxiety disorders (ASD, AGP, GAD, OCD, phobia, PD, PTSD, SAD)." (PMID 23908608, 2013). "Moreover, Brain-Derived Neurotrophic Factor (BDNF), generated during skeletal muscle contractions, has been recognized for its impact on the onset of anxiety disorders." (PMID 40373026, 2025). "Neuroimaging evidence indicates that in the PLWH with comorbid anxiety disorders, regional homogeneity (ReHo) in the right superior parietal cortex is negatively correlated with the initial CD4+ T cell count and brain-derived neurotrophic factor (BDNF) levels." (PMID 40176812, 2025). "Except for anxiety disorders and age, there were no other variables affecting levels of NfL, BDNF, or NfL/BDNF ratio in our sample." (PMID 36674698, 2023). "Findings are, however, limited by the lack of research in this area, and given the potential for BDNF as a biomarker of anxiety disorders, it would be useful to clarify the relationship further." (PMID 23908608, 2013). "In five of these reports, BDNF levels (both serum and plasma) in patients with an anxiety disorder were lower than in participants without an anxiety disorder, with effect sizes ranging from moderate to large." (PMID 23908608, 2013). "Initial findings suggested that BDNF levels were lower in individuals with any anxiety disorder compared to those without [Standard Mean Difference (SMD) = −0.94 (−1.75, −0.12), p ≤ 0.05]." (PMID 23908608, 2013). "Our initial results suggested that BDNF levels differ between individuals with any anxiety disorder compared to those without, with levels being lower in those with an anxiety disorder." (PMID 23908608, 2013). "Six of the eight studies included showed differences in BDNF protein levels between participants with an anxiety disorder and participants without." (PMID 23908608, 2013). "This was, however, dependent on source of BDNF protein [plasma: SMD = −1.31 (−1.69, −0.92), p ≤ 0.01; serum: SMD = −1.06 (−2.27, 0.16), p ≥ 0.01] and type of anxiety disorder [PTSD: SMD = −0.05 (−1.66, 1.75), p ≥ 0.01; OCD: SMD = −2.33 (−4.21, −0.45), p ≤ 0.01]." (PMID 23908608, 2013). "In this framework, altered peripheral BDNF levels have been reported in PTSD and it has recently been described how BDNF may have a role in fear extinction and combat impaired extinction in anxiety disorders and PTSD." (PMID 39062102, 2024). "However, the findings regarding the relationship between BDNF level and anxiety disorder are not consistent in either animal models or human studies." (PMID 33767622, 2021). "In summary, although there is evidence for lower peripheral BDNF in anxiety disorders, this seems to result specifically from lower BDNF in OCD, rather than other anxiety disorders." (PMID 23908608, 2013).